IL6 (interleukin 6)
Diseases named in the same sentence as IL6 in open-access papers (continued):
Sharing a sentence is not in itself a finding about the gene and the disease.
lupus (continued). "Here we demonstrated for the first time that lowering let-7f expression in SLE BM-MSCs might play a role in lupus pathogenesis through targeting IL-6." (PMID 32133007, 2020). "Normalizing ERK1/2 in lupus‐prone mice reduced expression of IL‐1β, TNF‐α and IL‐6 and relieved development of lupus." (PMID 33079487, 2020). "Activation of miR-654 reduced IL-1β, IL-6, IL-8, and TNF-α production, reduced gomerulonephritis, and decreased MIF, IgG, and C3 expression in murine lupus glomeruli." (PMID 31608058, 2019). "Serum cytokines of IFN- α, IL-6, IL-8, IL-17, and IL-18 correlate with SLE disease severity measured by Systemic Lupus Erythematosus Disease Activity Index (SLEDAI)." (PMID 31842967, 2019). "Of this proinflammatory cytokines, IL-6, IL-17, TNF-α, and IFN-α suppression have been reported as therapeutic targets for clinical management of lupus and other chronic inflammatory diseases." (PMID 31781106, 2019). "To investigate the contribution of IL-6 to the lupus phenotype, we crossed ABIN1[D485N] mice to IL-6 KO mice and found that splenomegaly was reduced and the formation of GCB cells abolished." (PMID 31694920, 2019). "Treatment of lupus prone NZB/W F1 mice with IL-6 exacerbated glomerulonephritis, whilst treatment with anti-IL-6 monoclonal antibodies in NZB/W F1 mice ameliorated kidney manifestations and reduced circulating anti-dsDNA autoantibodies titers." (PMID 31835612, 2019). "The phenolic fraction of extra virgin olive oil has anti-inflammatory and immunomodulatory properties that associated with a reduced production of pro-inflammatory TNF-α, IL-6, IL-1β, and IFN-γ in 38 lupus patients’ peripheral blood mononuclear cells (PBMCs)." (PMID 31137916, 2019). "Synergistic increases in the secretion of IL-6 upon hCG and ODN1826 co-incubation were, once again, restricted to cells derived from lupus-prone mice." (PMID 30574119, 2018). "In a clinical trial for anti-IL-6 in patients with systemic lupus erythematosus, we measure interferon (IFN) status, anti-IL-6 drug exposure, and whole blood genome-wide gene expression at three time points." (PMID 30340504, 2018). "More specifically, keratinocyte specific secretion of IFNκ increases after UVB treatment of lupus keratinocytes and neutralization of this type I IFN abrogates IL-6 production." (PMID 30405625, 2018). "In this study, we leverage the power of repeat transcriptional and environmental measurements from a lupus clinical trial to identify in vivo eQTL interactions with IFN status and anti-IL-6 exposure." (PMID 30340504, 2018). "For example, the highly connected TF IRF5 is associated with multiple autoimmune diseases, including multiple sclerosis and systemic lupus erythematosus (SLE), and leads to low type-I interferon, TNF and IL6 production in knockout mice." (PMID 30184180, 2018). "Thus, due to the reflection of PBMC IL-6 hypomethylation pattern in SLE, it is estimated to be a novel biological marker to predict lupus flares." (PMID 28785369, 2017). "Multiple effector mechanisms have been identified in lupus-prone mice and these include but are not limited to Fc receptors (FcRs), type I IFN receptors, IL-6, and MCP-151–54." (PMID 28663794, 2017). "Our findings revealed increased levels of IL-4, IL-6, IL-7, IL-12, IL-17, IFN-α, IFN-γ, TGF-β, BAFF and APRIL in lupus mice." (PMID 25909640, 2015). "Multiple cytokines have been implicated in playing key roles during the initiation, progression, and development of murine and human lupus including, but not limited to, IFN-, IL-17, IL-6, IL-1 and TNF-′." (PMID 25867237, 2015). "Our study also confirms and strengthens previous reports on increased levels of IL-6, IL-10, TNF-α, IFN-γ, IL-17 and IL-23 as well as low TGF-β in lupus patients." (PMID 25887118, 2015).
lupus (continued). "In SLE, for example, in situ expression of activated NF-κB is increased in glomerular endothelial cells, mesangial cells, and infiltrating cells in class IV lupus nephritis, along with upregulation of TNFα, IL-1β, IL-6, and ICAM-1 expression." (PMID 22701487, 2012). "It was found that TNF-α, IL-1β, IL-6, IL-12 and MCP-1, which were upregulated in kidneys of ALD-DNA-induced lupus mice, were decreased in the pSAP-treated lupus mice." (PMID 21799927, 2011). "Analysis of the cytokine profile in serum of mice further confirmed that the inflammatory markers (including TNF-α, IL-1β, IL-6, IL-12, and MCP-1) were extensively and dramatically decreased in pSAP-treated lupus mice as compared with other control groups." (PMID 21799927, 2011). "In another model, elicited peritoneal macrophages from lupus-prone New Zealand Black/White F1 (NZB/W) mice showed a unique cytokine production profile, with a higher amount of IL-6 and about a half amount of TNF-alpha following stimulation with DNA." (PMID 27713252, 2010). "While IL‐6 elevation is non-specific-occurring in active lupus, infections, and malignancies, its dramatic decline supported tumor-derived cytokine production." (PMID 41552135, 2025). "The study demonstrates their impact to reduced anti-dsDNA, ANA, and anti-RNP antibodies, alleviated proteinuria and disease severity, boosted CD4+ CD25+ FoxP3+ Tregs, lowered IL-6, and elevated IL-10 and TGF-β, collectively ameliorating SLE symptoms in pristane-induced lupus mice." (PMID 40534849, 2025). "Fli-1′s role in lupus may be partly due to the production of pro-inflammatory mediators such as IL-6 and CCL2, which have been alleviated in endothelial cells and splenic T cells in Fli-1 heterozygous lupus mice." (PMID 40305194, 2025). "In RA synoviocytes, where IL-6/JAK–STAT signaling drives synovitis, and in systemic lupus erythematosus (SLE), where interferon signatures dominate, adropin deficiency could contribute to unchecked STAT signaling." (PMID 41007860, 2025). "In addition, inflammatory pathways were also prominent, including IFN-γ response, IL-6/JAK/STAT3, systemic lupus erythematosus, TLR signaling, immunoglobulin-mediated phagocytosis, NK cell–mediated cytotoxicity, and allograft rejection." (PMID 38386415, 2024). "The correlation between gut mycobiota and lupus characteristics, including anti-dsDNA, urine protein creatinine index (UPCI), and serum cytokines (IL-6, TNF-α, and IL-10) were examined using the NMDS with length and direction of vectors to represent strength and direction of the association." (PMID 39637140, 2024). "Unlike what was observed in basophils from control mice, constitutive IL-4 and IL-6 productions were significantly detected in non-restimulated basophils from both lupus-like models, whereas no major differences were noticed after PMA-ionomycin restimulation." (PMID 38649353, 2024). "Moreover, we measured the serum levels of the anti-dsDNA antibody, IL-6 and IFN-γ, which are also hallmarks of lupus progression." (PMID 39053932, 2024). "Therefore, abrogation of IL-6 signaling appears to return the memory and learning functions of MRL/lpr mice to those of non-lupus controls, at least in this indirect comparison." (PMID 38600510, 2024). "Notably, monocytes from lupus patients diagnosed with low-to-moderate disease activity under stable conditions produced higher amounts of IFN-α and IL-6 than healthy monocytes after nucleic acid ligand stimulation." (PMID 36719379, 2023). "This IL-6 hyperproduction was type I IFN-dependent, as pretreating keratinocytes with type I IFN increased their IL-6 production, and type I IFN blockade decreased IL-6 secretion by the lupus patients’ keratinocytes." (PMID 36769633, 2023). "Naja naja atra snake venom and its toxin neurotoxin-Nna has been shown to decrease IL-1β and TNF-α levels in the kidney and the serum of rats, respectively; in addition, N. n. atra venom can inhibit IL-6 and TNF-α production in systemic lupus erythematosus in mice." (PMID 36828473, 2023).
lupus (continued). "Furthermore, IL-6 was shown to be increased in the cerebrospinal fluid of patients with lupus psychosis and to have an inverse correlation with hemoglobin levels in 171 patients with SLE." (PMID 37762312, 2023). "Deletion of either miR-183C or miR-182 alone had no changes on the serum levels of IFNγ, IL-6, or other selected lupus-related cytokines, such as TNFα, IL-10, and IL-17." (PMID 35873462, 2022). "Studies have shown that artemisinin can alleviate the levels of interleukin-6 (IL-6) and tumor necrosis factor-α (TNF-α) in the plasma of mice with systemic lupus erythematosus and inhibit the activities of nuclear factor‐kappa B (NF-κB) and transforming growth factor-β1 (TGF-β1) in the kidney." (PMID 35370688, 2022). "We found that the IL-6 concentration and the percentage of IL-6+ cells increased when the cells were differentiated in the presence of PRL, further supporting that PRL promotes IL-6 secretion in B-GCs in lupus-prone mice." (PMID 36389691, 2022). "In addition, since the CD90+αSMA+ mesangial cells are an important source of proinflammatory cytokines like IL‐6 and TNF‐α in kidney, the reduced mesangial cells in IL‐35p and Tregs‐treated lupus mice indicate an immunoregulatory functions of IL‐35 in vivo." (PMID 33634995, 2021). "This case control study used 46 KOA patients (pKOA, n = 30; sKOA, n = 16), and 60 age, gender matched controls (normal healthy, n = 30; systemic lupus erythematosus [SLE] disease controls, n = 30) where serum was assayed for cytokines (TNF-α, IL-1β, IL-6, IL-10) and nitric oxide derivatives (NOx)." (PMID 34543351, 2021). "We found that IL-6 and TNF-α production by B cells from IRF5-heterozygous mice was reduced by about half in response to combinations of stimuli that are thought to be involved in B cell activation in the GC in lupus." (PMID 34197340, 2021). "B cell–intrinsic IL-6 and TNF-α production have been shown to be important in GC formation in mice immunized with T-dependent antigens and in GC formation and disease pathogenesis in lupus and other autoimmune models." (PMID 34197340, 2021). "Nevertheless, the co-housing of asymptomatic lupus mice with the symptomatic lupus mice (with fecal gavage) also mildly activated serum IL-6 and anti-dsDNA Ig without increased gut-leakage." (PMID 31964918, 2020). "Serum proinflammatory cytokines, including IL-17a, IFN-γ, IL-6, TNF, and IL-2, were significantly increased, while the anti-inflammatory cytokine IL-10 was significantly decreased in sodium chloride-pretreated BMDC-ALD-DNA-induced lupus mice." (PMID 32296043, 2020). "Upon repeated injection of apoptotic cells, these mice developed a systemic lupus erythematosus (SLE)-like disease, with increased levels of pro-inflammatory cytokines, such as IL-6, IL-1β, IL-12, autoantibodies, and a decreased level of the anti-inflammatory cytokine, IL-10." (PMID 31665027, 2019). "According to previous research, miR-339-5p inhibited the expressions of the proinflammatory factors IL-6, IL-1β, and TNF-α by abolishing NF-κB activity and miR-361-5p is downregulated in interferon-positive antiphospholipid syndrome and systemic lupus erythematosus dendritic cells." (PMID 30854012, 2019). "In a mouse model of systemic lupus erythematosus (SLE), it was found that treatment with pan-HDACi trichostatin A (TSA) led to a decrease in mRNA expression of various inflammatory cytokines such as IL-6, IL-2, IL-10, and IFNγ." (PMID 31067680, 2019). "Thus, the aim of this research is to determine the plasma levels of IL-25 and Th2-associated cytokines (IL-4, IL-5, IL-6, IL-9, IL-10, IL-13) in SLE patients with (SLE-LN) and without lupus nephritis." (PMID 31697750, 2019). "Here, we review IL-6 and tocilizumab, an IL-6 receptor blocker, and survey the literature on off-label tocilizumab use in pediatric patients with rheumatic diseases, such as juvenile-onset systemic lupus erythematosus (SLE), juvenile dermatomyositis (DM), vasculitis, and juvenile scleroderma." (PMID 30547812, 2018).
lupus (continued). "Among the secreted pro-inflammatory cytokines/chemokines analyzed (IL-6, IL12p70, and CXCL10), the strongest suppressive effect was on CXCL10, a highly Type I IFN-dependent cytokine, upon CpG stimulation, both in normal and lupus-prone DCs." (PMID 29456540, 2018). "The discrepancy may have been due to different lupus-prone mouse models used or different activation methods (anti-CD40 versus LPS), although another study has shown that LPS could increase IL-6 production from BMDC of B6.Sle1.Sle2.Sle3 mice." (PMID 27034965, 2016). "In the lupus-prone (NZX × NZW)F1 (NZB/NZW) mice model, infiltration of CD3+ T cells and increased mRNA expression of pro-inflammatory mediators such as IL-1β, IL-6, IL-10, interferon (IFN)-γ and transforming growth factor β have been shown in the hippocampi ex vivo." (PMID 25955648, 2015). "In systemic lupus erythematosus, the exact mechanism by which IL-6 contributes to the disease pathology is not yet known; however, elevated serum IL-6 has been shown to correlate with B-cell hyperactivity and autoantibody production." (PMID 24670876, 2014). "Conversely, ALD-DNA did not enhance LPS-induced IL-6 expression (ALD-DNA plus LPS and LPS alone induced IL-6 at concentrations of 59 pg/ml and 63.2 pg/ml, respectively; data not shown) in lupus B cells." (PMID 25296026, 2014). "The protein product of IRF5, a lupus susceptibility gene, acts as a transcription factor to mediate TLR induction of proinflammatory cytokines IL-6, IL-12, TNFα and, to some extent, IFN-α, independent of NF-κB." (PMID 23557436, 2013). "With Syk inhibitor, lupus characteristics and systemic inflammation in FcγRIIb−/− mice were less prominent than the mice without inhibitor, as indicated by serum anti-dsDNA, proteinuria, and serum cytokines (TNFa but not IL-6)." (PMID 39962056, 2025). "Our data revealed amelioration of BTN3A1‐induced lupus‐like changes, such as improved degree of renal injuries and reduced percentage of CD3+, CD8+ T cells, Th1, Th2, Th17 cells, upregulated percentage of Treg cells, and lower expression of IL‐4, IL‐6, IL‐10, IL‐17A, IFN‐γ, TNF‐α, and dsDNA." (PMID 40959207, 2025). "The occurrence of systemic lupus erythematosus (SLE) is closely related to IFN: the combination of IFN-α and TNF can increase the chromatin accessibility of tolerance genes (such as IL6), leading to the appearance of tolerant monocytes." (PMID 38586584, 2024). "Similarly, FcγRIIb−/− lupus mice treated with etanercept upregulated cancellous bone volume and cortical thickness and downregulated expression of osteoblast marker genes (OSX, Collagen type I α 1) and serum levels of TNFα, IFNγ, IL-6, and IL-17A." (PMID 38164134, 2023). "Systemic Lupus Erythematosus (SLE) features excessive ROS production shaped by genetic factors like IFN-α, IL-1, IL-6, and TNF-α, highlighting the genetic facets of immune dysregulation." (PMID 38248493, 2023). "Patients with systemic lupus erythematosus (SLE) often display modest elevations of CRP despite raised disease activity and increased (IL-6)." (PMID 34680097, 2021). "It is notable that IL‐38 injection significantly reduced the levels of inflammatory cytokines IL‐1β, TNF‐α, IL‐6 and IL‐23 in plasma, demonstrating that IL‐38 is able to protect mice from lupus development, and has a negative role in regulating inflammatory cytokines both in vitro and in vivo." (PMID 33079487, 2020). "In an autoimmune disease, systemic lupus erythematosus (SLE), HDAC inhibitors were found to decrease the mRNA expression of inflammatory cytokines including IL-6, IL-12 and IFN-γ." (PMID 32183059, 2020). "The increased numbers of pMo and iMo in ABIN1[D485N] mice are, therefore, driven by the same MyD88-IRAK4-IRAK1 signaling pathway that drives lupus but, similar to the liver pathology, the increases in these monocytes are unaffected by the absence of IL-6 or an adaptive immune system." (PMID 31694920, 2019).
lupus (continued). "Other studies showed significant correlation between IL-6 and SLE, lupus nephritis, SLEDAI scoring, erythrocyte sedimentation rate (ESR), and C-reactive protein to IL-6 expression." (PMID 31697750, 2019). "In a mouse model of systemic lupus erythematosus (SLE), treatment with TSA resulted in decreased mRNA expression of several inflammatory cytokines, including IL-6, IL-12, and IFN-γ." (PMID 27556043, 2016). "Furthermore, stimulation of TLR7 with a synthetic agonist in lupus-prone mice lacking the alpha oestrogen receptor led to a lower IL-6 synthesis by lymphocytes B than in wild type animals." (PMID 24692849, 2014). "Disappointingly, treatment of SLE patients with an IL-6 inhibitor sirukumab revealed no obvious benefits in those developing Lupus GN but was associated with significantly increased adverse effect incidence." (PMID 39723211, 2024). "In addition, lupus IgG1-injected MRL-lpr/lpr mice exhibited significantly higher serum C3 and complement factors B and H levels, as well as significantly lower serum IFN-γ, IL-6, and IL-17 levels at 19 weeks of age, compared with those of control IgG1-treated and non-treated groups." (PMID 32625200, 2020). "Exosomes derived from lymphocytic leukemia (CLL) can target TLR7 signaling to promote innate immunity, while exosomes isolated from systemic lupus erythematosus (SLE) patients' serum can produce abundant IFN-α, TNF-α, IL-1β, and IL-6 via the TLR1/2, TLR7, TLR9, and TLR4 pathways." (PMID 32565722, 2020). "IL-9 and IL-10 showed a significant positive correlation with IL-25 in all 17 SLE patients with lupus nephritis, whereas a significant negative correlation was observed with IL-5 and IL-6." (PMID 31697750, 2019). "This study aimed to investigate whether serum levels of IL-6 and CIC correlated with SLE disease activity achieved by the Systemic Lupus Erythematosus Disease Activity Index (SLEDAI-2K) and modified SLEDAI-2K." (PMID 29422675, 2018). "Interestingly, endothelial activation, also associated with serum markers of the inflammatory process of SLE (low C4; increased CRP or IL-6), appears not to be associated with the SLE activity index (Systemic Lupus Erythematosus Disease Activity Index [SLEDAI])." (PMID 36622519, 2023). "MRL-Faslpr/lpr mice, the regulatory role of IL6 and CD40 in LPS-induced B cell differentiation is not evident, which might be related with elevated basal p-ERK level in lupus-prone B cells." (PMID 26068236, 2015). "Supplementation of C. zanthorrhiza with vitamin D3 was not able to decrease IL-6 level and elevate TGF-β1 systemic lupus erythematosus (SLE) in patients with hypovitaminosis D." (PMID 33995049, 2021). "We also measured the IL-6 concentration secreted by peripheral blood mononuclear cells (PBMCs) incubated with (a) oligonucleotide (CpG-B) in the presence or absence of recombinant human PGRN (rhPGRN); and (b) lupus sera in the presence or absence of a neutralizing anti-PGRN antibody." (PMID 23140401, 2012). "Furthermore, the serum CD200 level negatively correlated with the serum complement 3 level (r = -0.45, P = 0.014), but not the Systemic Lupus Erythematosus Disease Activity Index score or the levels of serum B-cell activating factor belonging to the TNF family, IL-6, IFNα, or anti-dsDNA (P > 0.05)." (PMID 22621248, 2012).